CD4 (CD4 molecule)
Diseases named in the same sentence as CD4 in open-access papers (continued):
Sharing a sentence is not in itself a finding about the gene and the disease.
lupus (continued). "We evaluated the gene expression of methylating enzymes, DNA methyltransferases (DNMTs), and demethylating ten-eleven translocation proteins (TETs) to elucidate the molecular basis of DNA hypomethylation in lupus CD4+ T cells." (PMID 38153351, 2023). "Recently, efforts have been made to use external IL-2 injection to increase CD4+CD25+CD127low Treg cells in vivo in lupus patients." (PMID 37736101, 2023). "The enhanced glycolysis and OXPHOS found in naive CD4+ T cells from lupus-prone mice correlated with cellular activation status, especially excessive interferon gamma (IFNγ) production." (PMID 37554724, 2023). "Propionibacterium propionicum and Bacteroides thetaiotaomicron, two of the identified commensal microorganisms, were regarded to activate Ro60-specific CD4+ memory T cells in lupus patients." (PMID 37621873, 2023). "There was a significantly elevated expression of Dnmt1 and Dnmt3b, as well as Tet1 and Tet2, in CD4+ T cells of three different lupus-prone mouse strains compared to controls." (PMID 38153351, 2023). "It has been noted that in vivo, B cells from lupus mice promote enhanced differentiation of CD4+ T cells into Th1 and Tfh cells while limiting the expansion of Treg cells to a greater extent than B cells from non-lupus mice." (PMID 38137363, 2023). "Autoantibody production and the clinical severity of lupus in NZBWF1 mice prone to the disease are contingent on the assistance of CD4+ T cells." (PMID 38137363, 2023). "The leading ID conditions were HIV infections (42.6%) with a median CD4 cell level of 81 cells/mm3 and systemic lupus erythematosus (SLE; 7.4%)." (PMID 37550721, 2023). "SLE patients’ CD4+ T cells have hypoacetylated histones, and treating lupus-prone mice with histone deacetylase inhibitors alleviated disease severity by downregulating proinflammatory cytokines." (PMID 37445926, 2023). "Reduced expression/activity of DNMT1 and/or DNMT3a/3b has been identified in the PBMCs or CD4+ T cells of human patients with lupus, which contributed to the DNA hypomethylation in human lupus cells." (PMID 38153351, 2023). "In this study, we reported that Egr2 deletion significantly reduced maternally expressed Dlk1-Dio3 miRNAs, suggesting that EGR2 plays an important role in the upregulation of Dlk1-Dio3 miRNAs in murine lupus CD4+ T cells." (PMID 38153351, 2023). "The aim of this study was to investigate the characteristics of CD4+CD40+ T cells (Th40 cells) in Chinese systemic lupus erythematosus (SLE) patients." (PMID 37400575, 2023). "Despite the well-accepted importance of autoantigen-specific CD4+ T cells in lupus, little is known about their characteristics and how their activation and expansion are controlled." (PMID 38022661, 2023). "Despite these studies in other diseases, the function and molecular mechanisms of circulating miRNAs in lupus CD4+ T cells are not well understood." (PMID 37928434, 2023). "The increase of Dnmt gene expression was also observed in the CD4+ T cells of other lupus-prone mice models, B6/lpr and B6.sle123." (PMID 38153351, 2023). "Of interest, Dex-NPs, but not dexamethasone, mediated the expansion of CD3+CD4+Foxp3+ Tregs and CD3+CD4+Foxp3+CD25+ activated Tregs in Fcgr2b-/- lupus-prone mice." (PMID 37176021, 2023). "Injection of the poly(lactic-co-glycolic acid) nanoparticle encapsulating TGF-β into lupus mice induced expansion of CD4+Foxp3+ Treg cells and CD8+Foxp3+ Treg cells and suppression of anti-dsDNA antibody and reduced renal disease." (PMID 38164134, 2023). "In lupus murine models, the percentage of Tfh cells increased and the Tfr (CD4+CXCR5+FoxP3+) cells decreased in 16-week-old MRL/lpr mice." (PMID 37771588, 2023).
lupus (continued). "To test the potential epigenetic regulatory role of EGR2 in lupus CD4+ T cells, we evaluated the expression of selected methylation-sensitive Dlk1-Dio3 miRNAs, which are highly upregulated in lupus (e.g., miR-127, miR-154, miR-300, miR-279, and miR-433)." (PMID 38153351, 2023). "Consistent with the high therapeutic potential of CD4+Lrig1+ T cells in IBD and lupus animal models, the higher expression of the genes involved in functions of Treg cells or induced by Foxp3 was observed in CD4+Lrig1+ T cells than CD4+Lrig1− T cells." (PMID 37666819, 2023). "Downregulated NSUN2 expression, along with decreased mRNA m5C levels of CD4+ T cells, was observed in systemic lupus erythematosus (SLE) patients, while the number of m5C-containing RNAs increased." (PMID 37325635, 2023). "We have reported that intracellular iron accumulation drives DNA hydroxymethylation and demethylation, promoting gene transcription and CD4+ T cell overactivation in lupus." (PMID 35499082, 2022). "We demonstrated that the overexpression of BCL-6 in CD4+ T cells in lupus decreased the expression of miR-142-3p/5p, and inhibition of miR-142-3P/5P, and led to increased expression of IL-21." (PMID 35637283, 2022). "Dysregulated mitochondrial function and fatty acid metabolism promoted tissue invasiveness of T‐cells in RA,41, 42 whereas CD4+ T‐cells from lupus patients were predominantly enhanced with glucose glycolysis and mitochondrial respiration." (PMID 35917405, 2022). "In this study, we have investigated the exact roles and relevant mechanisms of CD4+ T cells in abnormal IgG production using a pristane-induced lupus-like mouse model." (PMID 35095344, 2022). "MPA also activates miR-142 and miR-146a, both of which have been reported to negatively regulate CD4+ T-cell activation in lupus." (PMID 35159315, 2022). "T follicular helper (Tfh) cells are a subset of CD4+ T cells that are essential in the pathogenesis of systemic lupus erythematosus (SLE)." (PMID 35499081, 2022). "Another inhibitor, CG-5, inhibiting glucose transporters, is reported to ameliorate autoimmune phenotypes in TC lupus model, partially via the inhibition of glycolysis in CD4+ T cells." (PMID 36405760, 2022). "After two days of stimulation, Antagomir-21 reduced the expression of miR-21, the percentage of Tfh cells, and mRNA levels of Tfh signature genes in lupus CD4+ T cells." (PMID 35499082, 2022). "Considering pristane-induced lupus-like mouse model recapitulates most of the key immunologic and clinical features of human SLE, the role of pathogenic CD4+ T cell in the generation of pathogenic IgG in human SLE might be similar." (PMID 35095344, 2022). "And, a blockade of IGFBP2 elevated the ratio of Tregs inhibits the proliferation and activation of CD4+ T cells, thereby achieving the possibility of inhibiting the progression of lupus (P < 0.05)." (PMID 36008635, 2022). "To study the potential role of NK1.1+, CD4+ T cells in this mouse model of lupus, we firstly induced the production of IgG anti-NPA antibodies in C57BL/6 mice using liposomes bearing promazine-induced NPAs." (PMID 35877846, 2022). "CD4+ T‐cells from patients with rheumatoid arthritis (RA) and systemic lupus erythematosus (SLE) were used as disease controls." (PMID 35917405, 2022). "First, CD4 + T cells treated with H2O2 were injected into the tail vein of mice to establish a lupus model." (PMID 35001849, 2022). "The validity of this approach is supported by recent studies indicating that higher levels of Eomes in CD4 T cells correlate with an exhausted phenotype in Lupus patients with long-standing remission versus CD4 T cells in patients with active disease." (PMID 36358898, 2022). "In this study, we intended to clarify the interaction patterns of CD4+ T cells with B cells in promoting IgG production under the pathogenesis of lupus." (PMID 35095344, 2022). "CD4+ T cells from MRL/lpr lupus-prone mice also displayed higher iron content, which also supports a causal relationship." (PMID 35499081, 2022).
lupus (continued). "As one of the classic parameters examined in relation to lupus, the proportion of splenic effector memory CD4+ T cells has, for many years, been used to evaluate immune status in models of lupus." (PMID 35784310, 2022). "In juvenile onset lupus, CREMα has been recognized to drive increased IL-17A expression and reduced IL-2 production in CD4+ T cells." (PMID 35620115, 2022). "In this study, we investigated the manners of CD4+ T cells in antibody production in a lupus-like mouse model through peritoneal injection of pristane reagent." (PMID 35095344, 2022). "Accordingly, we also observed that the cells with the highest AIM2 levels were AIM2+ TFH‐like cells (CD4+PD1+Bcl6+AIM2+) in lupus patients." (PMID 35343082, 2022). "Next, combining time course sequencing (TCseq) with differentially expressed gene (DEG) analysis, crucial genes in lupus CD4+ T cells were revealed, including some interferon signature genes (ISGs)." (PMID 36046235, 2022). "Although MZ B cells undergo clonal expansion with aberrant autoantibody production and can enter lymphoid follicles to interact with CD4 T cells in lupus-prone mice, a recent study showed defective MZ B-cell differentiation in SLE patients." (PMID 36220996, 2022). "In animal experiments, CD4 was shown to induce LN when infused into lupus-prone mice with CD4+ T cell lines." (PMID 36532018, 2022). "CD4+ T cells from lupus patients and lupus-prone mice display high demand for glucose and depend on the rapid production of ATP, requiring both mitochondrial activity and cytoplasmic glycolysis." (PMID 35720293, 2022). "The trimethylation of histone H3 at lysine 27 (H3K27me3), in particular, leads to global gene silencing in animals, and increased H3K27me3 levels were reported in CD4+ T cells in lupus, compared with healthy controls." (PMID 35159315, 2022). "Overall, we provided supporting evidence that BCL-6 is a novel factor participating in the pathogenesis of lupus by epigenetically suppressing miR-142-3p/5p expression with the help of EZH2 in CD4+ T cells." (PMID 35637283, 2022). "In mouse models of lupus, activated T cells and increased frequencies of effector/memory CD4+ T cells have been reported repeatedly." (PMID 35055071, 2022). "We first injected H2O2 treated CD4 + T cells into the tail vein of mice to establish a mouse lupus mouse model, as we did before." (PMID 35001849, 2022). "BCL-6 attaches to the promoter region of miR-142 in CD4+ T cells in lupus and recruits EZH2 and HDAC5, which leads to the upregulation of H3K27me3 and the downregulation of H3K9/K14ac, respectively." (PMID 35637283, 2022). "In addition to the humoral response against β2GPI, both peripheral and tissue CD4+ β2GPI-specific T cells have been reported in primary APS as well as in systemic lupus erythematosus (SLE)-associated APS." (PMID 36700193, 2022). "In general, the DNA of lupus CD4+ T cells is hypomethylated, which activates immune-related gene expression in a distinct CD4+ T-cell subtype and correlates with SLE disease activity." (PMID 35159315, 2022). "In vitro, NaCl induced the DNA hypomethylation of CD4+T cells from systemic lupus erythematosus patients." (PMID 35565757, 2022). "Elevated blood levels of IFNλ3, as well as increased IFNL2 and IFNL3 mRNA have been detected in blood CD4+ T cells of lupus-prone mice and patients." (PMID 35833127, 2022). "EZH2 expression is elevated in CD4+ T cells in lupus, leading to increased cytokine secretion and increased T cell adhesion." (PMID 36313363, 2022). "In CD4+ T cells, dysregulated m5C modification was examined, and target mRNAs were related to systemic lupus erythematosus (SLE) pathogenesis." (PMID 35433474, 2022). "Our previous work demonstrated that miR-21 targets BDH2 to promote iron accumulation in lupus CD4+ T cells." (PMID 35499082, 2022).
lupus (continued). "In an in vivo study, silencing of miR‐21 under a tiny seed‐targeting locked‐nucleic acid (LNA) reversed splenomegaly resulted in approximately 20% de‐repression of programmed cell death 4 (PDCD4) in naïve CD4+ T cells and recovery of lupus mice." (PMID 35707883, 2022). "A new mechanism revealed by us indicates that BCL-6 recruits EZH2 to the promoter of miR-142 in CD4 + T cells in lupus to increase the expression of miR-142-3p/5p." (PMID 35637283, 2022). "CXCR5+PD1+CD4+ T cells were detected at much lower frequencies in lupus-prone MRL/lpr mice that had been treated from eight to 20 weeks of age, However, these T cells were not affected in MRL/lpr mice treated with CGS-21680 after disease onset." (PMID 35064115, 2022). "Cytokine production, complement activation, and clonal B cell activation secondary to CD4+ T cellular immune disorders in lupus lead to the overproduction of autoantibodies and tissue damage." (PMID 36313363, 2022). "Our study demonstrates that insufficient iron promotes Treg cell expansion by reducing ROS accumulation in CD4+T cells, leading to the improvement of pristane-induced lupus." (PMID 35296076, 2022). "This pathway is abnormally activated in lupus and very likely involved in the presentation of self-antigens to autoreactive CD4+ T cells." (PMID 35720371, 2022). "The previous study revealed that glycolysis was increased in CD4+ T‐cells and inhibition of glucose metabolism ameliorated disease of lupus." (PMID 35917405, 2022). "In the context of T cell-associated genetic alterations, the Sle1a gene segment in the NZM2410 lupus-prone strain is responsible for the increased activation of conventional CD4+ T cells (Tcon) and for the low numbers of CD4+FoxP3+ Treg." (PMID 36389689, 2022). "Adoptive transfer of procainamide-treated mouse CD4+ T cells elicits lupus-like autoantibodies and glomerulonephritis in vivo." (PMID 35983030, 2022). "Consistent with the findings in the scleroderma-like cGVHD model, we found that the frequencies of TNF-ɑ-and IL-4-expressing CD4+T cells were significantly increased in the spleens of lupus-like recipients with IL-39 plasmid treatment." (PMID 35655245, 2022). "The role of activated blood CD4+ T lymphocytes in patients with systemic lupus erythematosus (SLE) has been less studied." (PMID 35955790, 2022). "A CD4 T cell population in untreated lupus patients PBMC produces IFN-γ in response to histone peptide autoepitopes, and this autoimmune IFN-γ production response was almost completely suppressed in fresh PBMC from lupus patients in remission post-transplant." (PMID 33936042, 2021). "In this study, we found that ex vivo expression of BTLA on CD4+ T cells (both naive and memory) and on cTFH was comparable between lupus patients and healthy individuals." (PMID 34899718, 2021). "A recent study revealed that TET2 and TET3 are significantly increased in human lupus CD4+ T cells, correlating with increased 5hmc levels at promoter regions and gene activation in human lupus CD4+ T cells." (PMID 34062726, 2021). "mTOR inhibits the development of CD4+CD25+forkhead box P3(FoxP3)+ regulatory T cells (Tregs), which are deficient in lupus patients." (PMID 34239993, 2021). "It has been reported that unregulated EZH2 activation in CD4+ T cells leads to T cell activation and non-Th1 immune responses, prior to transcription activity, and is related to lupus activity." (PMID 33679454, 2021). "We found that lupus patients exhibited significantly reduced percentages of CD4+FoxP3+ (p < 0.0041) and CD8+FoxP3+ T cells (p < 0.0102) when compared to healthy controls." (PMID 33746959, 2021). "As HVEM plays a pivotal role in Treg-mediated suppression in mice, we compared the ex vivo expression of HVEM on peripheral CD4+ T cells and Tregs between HC and lupus patients." (PMID 34899718, 2021). "In accordance with our study, the application of in vitro-generated polyclonal IL-10-producing CD4 T cells to severely-ill NZB/W F1 mice improved lupus pathology." (PMID 33572870, 2021).
lupus (continued). "Adoptive CD4+ T cell therapy in one case of lupus with skin disease revealed evidence of T reg activation." (PMID 34211471, 2021). "When the CD4+ T cells from lupus mice were cultured with PD-L1 positive MDSCs from lupus and/or control mice, only PD-L1 positive MDSCs obtained from control mice markedly inhibited proinflammatory Th1, Th17 cells and reciprocally induced Foxp3+ Treg cells." (PMID 33986739, 2021). "Thirty-six upregulated miRNAs in human lupus CD4+ T cells were located near the hypomethylated sites, and eight downregulated miRNAs were hypermethylated in the lupus CD4+ T cells." (PMID 34062726, 2021). "MRLlpr lupus mice treated with nanolipogels loaded with 5Aza and tagged with anti-CD4, or -CD8 monoclonal antibodies ameliorated skin rash, proteinuria glomerular damage is reduced, and the inflammatory infiltration is decreased." (PMID 34769338, 2021). "Human Ro60 autoantigen–specific CD4 memory T cell clones from lupus patients react to Bacteroides thetaiotaomicron containing Ro60 orthologs." (PMID 34335588, 2021). "Since low oxidative stress and altered CD4+CD25+ Tregs are essential for safe pregnancy, lupus pregnancies are at high risk for potential complications such as pre-eclampsia and miscarriage." (PMID 34945017, 2021). "The overexpression of SIRT1 was found in CD4+ T cells of a murine lupus model, however, SIRT1-null mice showed with immunoglobulin deposition in the kidneys and a high level of serum antinuclear antibody." (PMID 34887866, 2021). "In the present work, we aimed at delineating the expression pattern of BTLA on CD4+ T cell subsets suspected to play a key role in lupus pathogenesis, such as circulating follicular helper T cells (cTFH) and regulatory T cells (Tregs)." (PMID 34899718, 2021). "LOX-1+ M-MDSCs promoted the accumulation of Th17 cells and inhibited the differentiation of Treg cells, LOX-1+ M-MDSCs, and LOX-1− M-MDSCs from mice with lupus were co-cultured with CD4+ T cells from normal mice in different conditional media." (PMID 34480018, 2021). "We found that SDMCs sorted from MRLlpr mice during lupus progression were able to suppress the proliferation of autologous CD4+ T cells and to promote their polarization toward Th1 cells." (PMID 33643317, 2021). "From these microarray data, we found that 1887 lncRNAs and 3375 mRNAs were differentially expressed in lupus CD4+ T cells compared to the healthy controls." (PMID 34707498, 2021). "Nevertheless, other studies demonstrated unchanged DNMT1 and even increased DNMT3a/3b expression in human lupus PBMCs or CD4+ T cells, despite the consistency of DNA hypomethylation in these lupus cells." (PMID 34062726, 2021). "We found that the expression of human ESRRG, which is high in Tregs, was lower in CD4+ T cells from patients with lupus than in healthy controls." (PMID 34156979, 2021). "Later studies in lupus CD4+ T cells demonstrated that ultraviolet B strongly activates AhR, which subsequently contributes to the low expression of SIRT1 by binding to the SIRT1 promoter." (PMID 33981300, 2021). "A recent study has reported reduced mRNA m5C levels in CD4+ T cells from patients with systemic lupus erythematosus (SLE) compared with CD4+ T cells of healthy controls (HCs)." (PMID 33912158, 2021). "It has been reported that DNMT1 and/or DNMT3a/3b expressions were significantly decreased in human lupus PBMCs and CD4+ T cells when compared to those of healthy controls, which correlated with the global DNA hypomethylation in the cells." (PMID 34062726, 2021). "Of the 47 differentially methylated genes identified in lupus naïve CD4+ T cells, 35 genes (75%) were hypomethylated." (PMID 34062726, 2021). "Here we aimed to explore aberrant expression of tRFs in CD4+ T cells from patients with systemic lupus erythematosus (SLE) and their potential function in the SLE pathogenesis." (PMID 34256772, 2021).